CD34 (CD34 molecule)
Diseases named in the same sentence as CD34 in open-access papers (continued):
Sharing a sentence is not in itself a finding about the gene and the disease.
tumor (continued). "PB smears of Eed+/Δ mice and siEED-transduced human CD34+ cord blood cells exhibited dysplasia in multilineage closely resembling the phenotype of MDS, indicating that suppressive expression EED underlies the morphological abnormalities observed in MDS and related neoplasm." (PMID 27432459, 2016). "Finally, we observed strong positivity for the CD31+ and CD34+ vasculo-endothelial cells in the xenografts grown from the cancer spheres, arguing that the isolated cancer spheres were indeed enriched in multipotent cancer stem cells/tumor initiating cells." (PMID 25011053, 2015). "Furthermore, in 1 case of a GBM, CD34 stained not only endothelial cells, but also tumor cells." (PMID 25881913, 2015). "In the non-tumour control cells (CD34+HSC and CD133+HSC), all polyphenols were shown to reduce the toxicity of topoisomerase II inhibitors on ATP levels and caspase 3 activity, suggesting polyphenols could be protective in normal cells, and hence could reduce off-target effects." (PMID 27551472, 2015). "In this present study the fact that CD34 is expressed at a higher level on tumor ECs could be due to circulating endothelial progenitor cells, which might be involved in the vasculogenesis of the tumor." (PMID 24632811, 2014). "Therefore, we speculate that loss of CD34 fibrocytes and gain of SMA myofibroblasts might be initiated by a soluble factor secreted by tumor cells and especially TGF-ß." (PMID 25011545, 2014). "In addition, staining with murine CD34 antibody demonstrated a strong inhibitory effect of PD0325901 on tumor vascularization, as control tumors contained large vessels, while treated tumors displayed drastically compromised vasculature composed by minuscule vessels." (PMID 24238212, 2013). "To examine whether these CD34− cells were tumor cells, we double-stained CD34 and nestin." (PMID 23536763, 2013). "Therefore, modulation of the expression of CD34 could be one explanation of the role of necrosis in tumor invasion." (PMID 23469238, 2013). "Furthermore, CD34 staining was performed to evaluate the MVD in the tumor." (PMID 22895629, 2012). "To assess whether loss of CD34 on hematopoietic or non-hematopoietic cells was responsible for the altered tumor growth observed at day 14, we generated bone marrow-reconstituted chimeras." (PMID 21494591, 2011). "Since we have previously shown a role for CD34 in both mast cell and eosinophil trafficking, we speculated that CD34 ablation would affect immune cell recruitment into the tumor microenvironment, with direct effects on tumor growth." (PMID 21494591, 2011). "Our previous studies have demonstrated a key role for CD34 in optimal eosinophil migration in vivo and in vitro and we speculate that increased tumor growth at the late time-point in Cd34−/− mice may also be due in part to impaired eosinophil migration, resulting in reduced tumor clearance." (PMID 21494591, 2011). "We propose that endothelial-expressed CD34 is most important for early tumor growth by maintaining vascular integrity, but the reduction in mast cell accumulation in Cd34−/− mice may also alter angiogenesis and play a minor role at the early time-point (day 14)." (PMID 21494591, 2011). "Thus, CD34 is required for efficient early tumor growth of both s.c. and i.v.-injected tumors." (PMID 21494591, 2011). "In addition, progesterone may participate as growth factor in many CD34(+) neoplasms, which expresses low levels of the hormone receptors." (PMID 19384025, 2009). "The cytogenetic similarities encountered in these two morphologically distinct entities, namely losses in 16q and gains in 1q chromosomes, might justify for the absence in our study, of tumor-microenvironment alterations, for both lesions, regarding the expression of CD34 and SMA." (PMID 18384688, 2008).
tumor (continued). "This hypothesis provides explanation for the phenotypic heterogeneity of these neoplasm and their variable IHC profiles taking into consideration the well-known inherent plasticity of the "vimentin+/CD34+ cell" to differentiate toward several mesenchymal lines." (PMID 16859566, 2006). "We hypothesised that our analyses within the tumour microenvironment mimicked the progressive ‘endothelial-like switch’ of CD11c+ leukocytes observed in vitro, which appeared to first acquire CD34, increase CD31 expression, and progressively lose the expression of the haematopoietic marker CD45." (PMID 15785750, 2005). "In contrast, MVD identified by CD34 (and other pan-endothelial markers) may not be able to accurately characterise angiogenesis of certain types of tumour, leading to a lack of association of MVD with tumour progression." (PMID 12778073, 2003). "In addition, because the tumour angiogenesis was also reported to be essential to tumour growth and metastasis, we evaluated intratumoural microvessel density (IMD) using anti-CD34 monoclonal antibody to study the correlation between N-cadherin expression and tumour angiogenesis." (PMID 12771988, 2003). "This increase could be related to tumour-derived factors that may either promote the mobilisation of CD34+ cells from the bone marrow, such as GM-CSF, or inhibit DC maturation from CD34+ precursors, such as VEGF, M-CSF and IL-6." (PMID 14562018, 2003). "CD31 and CD34 immunostaining revealed increased microvessel density in both the high and average vessel density regions of mucinous (222.4 +/- 24.8; 79.9 +/- 8.5) compared with serous (105.4 +/- 20.7; 33.3 +/- 6.8) and benign (84.4 +/- 19.4; 20.4 +/- 4.4) tumours (P < 0.001)." (PMID 9649134, 1998). "Parameters assessed included patient demographics, tumor location, histological subtype, mitotic index, and immunoreactivity for CD117, DOG1, and CD34." (PMID 42226834, 2026). "On the other hand, CD34 is often used to assess the microvessel density (MVD) of tumour tissues, including NSCLC, and is closely related to tumour angiogenesis, invasiveness, and microenvironmental constitutive cellular activity." (PMID 41579221, 2026). "Histological assessment of whole tissue sections of samples harvested at 48 hrs revealed significantly higher necrosis and CC3 staining, and significantly lower Ki67, CD34 and VEGFR2 staining, in tumours from the cabozantinib-treated Th-MYCN mice." (PMID 40359728, 2025). "In contrast, PAK4KO tumours exhibited significant increases in the expression of both CD31 and CD34, indicating extensive endothelial proliferation and the coexistence of mature and immature vascular networks." (PMID 41294859, 2025). "Histopathological characterization and immunohistochemical staining, particularly CD34 in combination with Bcl‐2 and STAT6, are the basis for diagnosing this tumor." (PMID 41409894, 2025). "Decreased tumor angiogenesis was demonstrated by downregulated expression of pro-angiogenic markers VEGF-A, CD31 and CD34." (PMID 41249582, 2025). "Immunohistochemical (IHC) staining further confirmed the tumor's smooth muscle and mesenchymal origins, with positive for Vimentin, SMA, Syn, Actin, Desmin, and CD34." (PMID 39776317, 2025). "Immunohistochemical staining for CD31, CD34, and FLI-1 supports the diagnosis of a borderline-malignant tumor." (PMID 40428263, 2025). "Immunohistochemical analysis revealed that the tumor cells expressed endothelial cell markers, including CD31, CD34, and ERG." (PMID 40797498, 2025). "Double staining with CD34 and PAS is a classic method for identifying tumor vascular structures and VM." (PMID 39802612, 2025). "Immunohistochemical profiling showed CD117 (+), CD34 (+), Desmin (-), DOG-1 (+), Ki67 (approximately 5% positive tumor cells), S-100 (-), SDHB (+), SMA (a few cells +), and SOX-10 (-)." (PMID 40365338, 2025). "IHC analysis showed that CD34 and CD105 expression differed among the heterogeneous tumor vasculatures." (PMID 41210695, 2025).
tumor (continued). "Since tumour angiogenesis is a key factor in the growth and metastasis of HCC, we proceeded to examine the expression of the endothelial cell surface marker CD34 in tissue microarrays." (PMID 40263693, 2025). "The lowest MFI were observed in CD34+/CD38+ cells and in H69 cells, which are a SSTR2-low expressing tumor model." (PMID 40521188, 2025). "Given that ASPLT is defined by a certain immunophenotype - CD34 and desmin positivity with Rb protein loss - the absence of IHC data raises concerns about the reliability of these diagnoses and limits their value in refining our understanding of the tumor’s defining features." (PMID 41527615, 2025). "Immunohistochemistry typically reveals positivity for CD31, CD34, and ERG (erythroblast transformation-specific related gene), consistent with the vascular origin of the tumor." (PMID 40979823, 2025). "Its co-localization with endothelial markers CD34 and CD105 further supports the role of the CXCR4 receptor in tumor vascularization and endothelial cell proliferation in MOC tumors." (PMID 41210695, 2025). "Additionally, MST is characteristically CD34-positive and may harbor a BRAF V600E mutation, whereas this tumor was CD34-negative." (PMID 39857780, 2025). "For example, we discovered specific highly-expressed pairs KDR-PECAM1, KDR-CDH5, and CD34-SELL between immune cells and malignant tumor cells, thus these genes play an important role for the control of cancers." (PMID 41282090, 2025). "Among the IHC markers, TRK, CD34 and S-100(especially TRK) are considered valuable for raising suspicion of this tumor type and guiding further molecular investigations." (PMID 40936706, 2025). "PAK1 knockout inhibited angiogenesis within the tumour by decreasing the intra-tumoral expression of CD31 and CD34, two common endothelial cell markers responsible for angiogenesis." (PMID 41228228, 2025). "CD34 and PAS staining are frequently applied to identify endothelial structures in tumor tissue and basement membrane structures in the tumor vasculature, respectively." (PMID 39802612, 2025). "Human M-CSF promotes the development and maturation of human phagocytic monocytes and macrophages, which appears to drive the low RBC count observed in CD34+-cell-engrafted NSG-Quad and MISTRG-6 mice, and restricts the time window for tumor xenograft studies." (PMID 40503011, 2025). "The positive staining for CD31, CD34, and ERG in combination with marked proliferation of the tumor, as expressed by proliferation index Ki-67, and the trajectory of the clinical course were the pointers to the correct diagnosis." (PMID 40255814, 2025). "Immunohistochemically, the tumor was positive for CD10, CD34, TLE1, estrogen, and progesterone receptors." (PMID 40878061, 2025). "This was accompanied by increased angiogenesis, as reflected by elevated CD31 and CD34 expression, with higher fibronectin deposition in PAK4KO tumours." (PMID 41294859, 2025). "To detect the co-localization of CXCR4+ vascular structures with endothelial markers, we stained tumor tissues of both MOC1 and MOC2 in serial sections with CD105, CD34, and D2-40." (PMID 41210695, 2025). "Immunohistochemically, the tumor showed strong positivity for CK19, CK7, and CD34 in ductular–trabecular structures, as well as glypican-3 and TTF-1 in solid components." (PMID 40843884, 2025). "The pathological specimens were analyzed for programmed death ligand 1 (PD-L1), Glypican-3, CD3-tumour infiltrating lymphocyte, CD68 positive cells, CD34 positive microvessel density (MVD)." (PMID 40640280, 2025). "In short, we identified an exclusive tumor cell subpopulation MP3 in D‐TGCT and confirmed the role of these tumor cells in regulating differentiation of CD34+ Fbs toward APOE+ Fbs and MMP3+ Fbs through COL6A3 − (ITGAV + ITGB8) interaction." (PMID 40126353, 2025).
tumor (continued). "Together, these results identified that the CD34+CLDN5+ cells (cluster 11) as a subtype of ECs during the progression of HCC, which significantly existed in tumor tissue and closely related with senescence." (PMID 39674501, 2025). "In cases of suspected CD117-negative GIST, a panel of markers, including DOG1, CD34, S-100, SMA, CD21, ALK, and desmin, should be used to differentiate this tumor from gastric CFTs." (PMID 40356746, 2025). "This implies that the CD34+ and CD105+ vessels have different characteristics within the tumor stroma." (PMID 41210695, 2025). "We have innovated a platform to reconstitute an autologous human immune system (HIS) in immunodeficient NOG-EXL mice from mobilized peripheral blood (MPB)-CD34 cells, along with PDX generated from the same patient’s tumor tissue." (PMID 40508078, 2025). "Endothelial cells and vascular endothelial cells on the tumor surface express CD31 and CD34, with a Ki-67 proliferation index of <5% and ≥5% in 34 and 9 patients, respectively." (PMID 40276735, 2025). "Histopathological confirmation was obtained via liver biopsy or surgical specimen, with immunohistochemistry performed to assess tumor differentiation using markers such as CK7, CK19, CK20, CK AE1/AE3, glypican-3, TTF-1, and CD34." (PMID 40843884, 2025). "Excisional biopsy from the right thigh lesion showed cohesive tumor cells with epithelioid to spindled morphology in a fibrotic background, vascular involvement, and immunopositivity for vascular markers (CD31, CD34, ERG, and factor VIII)." (PMID 38374236, 2025). "We have also examined the expression of several tumor aggressiveness markers (MMP‐9, CD44, CD34, PTTG, FGFR4, Ki‐67, E‐Cadherin, and N‐Cadherin) in AF, AD, and PF tumor cells of male rat pituitaries." (PMID 41017273, 2025). "A giant pelvic tumor was detected, and after surgery, the tumor was diagnosed as GIST based on histopathology, showing spindle cell proliferation and positive markers for c-kit, CD34, and DOG1." (PMID 40507589, 2025). "We observed increase expression of angiogenesis markers CD34 and CD31 and a significant upregulation of Vegf-a gene in tumor tissues." (PMID 41249582, 2025). "The distribution of TAMs in the deepest tumor infiltration zone was examined using fluorescent double staining (CD68: macrophages, CD34: vascular endothelial cells)." (PMID 40243510, 2025). "Knockout of PAK1 or PAK4 inhibited angiogenesis within the tumour by decreasing the intra-tumoral expression of CD31 and CD34, two common endothelial cell markers responsible for angiogenesis." (PMID 40943273, 2025). "Our tracking of MSC marker expression revealed progressive CD34 upregulation alongside declining ALCAM, CD44, and ICAM1 levels, indicating complex transcriptional reprogramming during MSC-to-tumor cell transitions." (PMID 40959090, 2025). "The tumor was successfully excised via an endonasal endoscopic approach, and histopathological analysis confirmed the diagnosis of an SFT with positive CD34 and CD99 markers." (PMID 40709355, 2025). "IL‐33 can upregulate the expression of endothelial adhesion molecules (PECAM1 and CD34) and organoid adhesion molecules (KRT17), thus promoting angiogenesis (cell‐to‐cell adhesion) and tumor proliferation." (PMID 40860436, 2025). "This interaction further promotes the expression of VE-cadherin, CD34, and SERPINE2, thereby facilitating the formation of vessel-like network structures by tumor cells." (PMID 41019994, 2025). "IHC of postoperative pathological sections confirmed high expression of ERG, FLI1, CD34 and PECAM1 in tumor cells." (PMID 41445863, 2025).
tumor (continued). "Co-localization of EphB4/ephrin-B2 with CD34 in stromal microvessels and GFAP in tumor cells has been observed, with higher expression levels in poorly differentiated tumors, reinforcing its relevance to both tumor aggressiveness and vascular pathology." (PMID 41200151, 2025). "Immunohistochemistry results were as follows: CD117 (+), CD34 (+), Desmin (-), DOG-1 (+), Ki67 positivity in approximately 5% of tumor cells, S-100 (-), SDHB (+), SMA (few cells +), SOX-10 (-)." (PMID 40365338, 2025). "Immunohistochemically, the tumor cells in PHA demonstrate positivity for vimentin and the vascular lineage markers, including ERG, CD31, CD34, FLI-1, and factor VIII-related antigen." (PMID 41367857, 2025). "We further performed IHC on these tumours, and the ACADS-OE tumours had decreased staining intensities of Ki-67, PCNA, and CD34 when compared to NC tumours." (PMID 39800718, 2025). "In PAK1KD tumours, a marked reduction in CD31 with an unchanged CD34 expression suggests suppressed angiogenesis, which is consistent with reduced VEGFA levels." (PMID 41294859, 2025). "In summary, we identified a novel subset of CD34+CLDN5+ECs, with distinct senescent cellular features and high expression of IGF2, which was regulated by CEBPβ, primarily existed in the HCC tumor tissue." (PMID 39674501, 2025). "IHC staining for CD34 and PAS staining demonstrated enhanced tumor angiogenesis, as evidenced by a higher microvessel density in the HepG2SG group compared to the HepG2-NC group (**p< 0.01)." (PMID 41476965, 2025). "The tumor is positive for high mobility group A2 (HMGA2), estrogen receptors (ERs), a cluster of differentiation 34 (CD34), and desmin immunomarkers." (PMID 39803071, 2024). "The combination of NZ + PT decreased tumor growth in wild-tipe tumor, with a very limited effects in NSG mice compared to the effects achieved in Hu-CD34+ mice." (PMID 39107857, 2024). "There was a correlation between tumor size, primary site, resection type, Ki67 index, neutrophil lymphocyte ratio (NLR) and CD34 expression and postoperative recurrence or metastasis of GISTs (P < 0.05)." (PMID 38395931, 2024). "Most of the tumor cells were positive for the glial fibrillary acidic protein (GFAP), CD34 (diffuse cytoplasmic and membranous positivity), with focal expression of Neu-N and synaptophysin on immunohistochemical analysis (IHC)." (PMID 39409964, 2024). "Immunohistochemistry showed the positive expression of CD31, CD34, α-SMA, GLUT1 and WT-1 in the tumor tissue, and the tumor was eventually diagnosed as an infantile haemangioma." (PMID 38267947, 2024). "The tumor was pathologically identified as angiosarcoma due to the expression of tumor-positive markers: CD31, CD34, ERG, and Ki-67." (PMID 38669418, 2024). "The morphological characteristics of vascular formations in BCC are influenced more by the tumor’s location and dissemination pattern than by the expression levels of angiogenic markers CD31 and CD34." (PMID 39399171, 2024). "HE staining demonstrated that GEB intervention considerably inhibited tumor angiogenesis and suppressed the expression of CD34 and VEGF in tumor tissue." (PMID 38915466, 2024). "On immunohistochemistry, the tumor cells were diffusely and strongly positive for STAT6, BCL2, and CD34." (PMID 39021462, 2024). "The tumors retained the characteristics of the original tumor, as confirmed through hematoxylin and eosin staining and histochemical analysis using markers such as AE1/3, desmin, S-100, CD34, and vimentin." (PMID 39737254, 2024). "significantly downregulated the protein and mRNA levels of Epidermal Growth Factor Receptor (EGFR), VEGF and the Cluster of Differentiation 34 (CD34) transmembrane cell-cell adhesion factor in tumour-bearing BALB/c mice, thereby inhibiting tumour growth." (PMID 39683144, 2024). "To explore the spatial relationship between pS6+ tumor cells and blood vessels, we sought to immunolabel UTUC tumors for pS6 alongside CD34 to stain vascular endothelial cells." (PMID 39133649, 2024).